HIF1A (hypoxia inducible factor 1 subunit alpha)
Diseases named in the same sentence as HIF1A in open-access papers (continued):
Sharing a sentence is not in itself a finding about the gene and the disease.
tumor (continued). "We demonstrate here that the molecular mechanism for engagement of NAMPT in promoting M2‐like TAM polarization in response to tumor‐derived lactate is via HIF‐1α stabilization through providing a NAMPT‐dependent sufficient NAD supply for lactate to pyruvate conversion." (PMID 38308188, 2024). "Hypoxia is a common feature of solid tumors, and tumor cells and normal cells adapt to the tumor microenvironment by upregulating the transcription factor hypoxia-inducible factor (HIF)-1α, which can be detrimental to anti-tumor effector immune cell function, including that of NK cells." (PMID 38892084, 2024). "Recently, evidence has suggested that HIF-1α serves as the main driver of ferroptosis resistance in tumour cells under hypoxic conditions through the generation of a lactate-induced acidic environment and enhancement of the transcription of the glutamate transporter SLC1A193." (PMID 38993573, 2024). "Previous studies on solid tumors demonstrated that HIF-1α blockage could inhibit PD-L1 expression to influence the anti-tumor effect, thus providing a rationale for combination therapies with immunotherapies." (PMID 38609977, 2024). "Thus suggesting that THC can inhibit tumor angiogenesis in caski transplanted nude mice via downregulation of HIF-1α and VEGF as well as its receptor’s expression levels." (PMID 38751791, 2024). "Since HIF1α plays a critical role in tumor angiogenesis, we also examined whether the anti-angiogenesis role of TRIM55 is dependent on HIF1α." (PMID 39420007, 2024). "In addition to increasing glucose metabolism, HIF-1A enhances glucose uptake by the tumor cells by inducing the activity of glucose transporter proteins GLUT1 and GLUT3." (PMID 39567394, 2024). "Early tumor hypoxia may induce the formation of CTC clusters with high metastatic potential through the HIF-1α pathway." (PMID 39434182, 2024). "Comparison of clinicopathological parameters according to tumor HIF-1α expression level." (PMID 39723370, 2024). "The expression of HIF-1α mRNA may be a potential driving factor for tumor growth and metastasis, and HIF-1α is a downstream transcription factor of mTOR." (PMID 38771435, 2024). "HIF-1α is a further crucial regulator of the tumor hypoxic microenvironment." (PMID 39683818, 2024). "The PI3K/AKT signaling pathway is a pivotal axis for multiple upstream signaling in tumor cells, aggregating and regulating many downstream transcriptional targets, including mTOR (regulates HIF‐1α and c‐Myc on downstream), Forkhead box protein O1 (FoxO1), GSK3, and other key molecules." (PMID 39584783, 2024). "The inhibition of HIF-1α expression may serve as an effective strategy to suppress tumor growth and metastasis, prompting the investigation of HIF-1α inhibitors." (PMID 38794281, 2024). "First, using scRNA-seq, Western blotting, and metabolic tracing, we showed that JHU083 had a direct antitumor effect on tumor cells and induced apoptosis after a global metabolic shutdown, a reduction in HIF-1α expression levels, and decreased phosphorylation of c-Myc." (PMID 38701369, 2024). "Additionally, tumor cells activate TAMs through the TLR4/TRIF/NF-κB signaling pathway and upregulate HIF1α-mediated IL-1β production to stimulate EMT of tumor cells." (PMID 38957393, 2024). "Further investigations may uncover specific downstream targets of HIF-1α that modulate the antitumor function of CAR T cells in the tumor microenvironment." (PMID 38425341, 2024). "We also observed that the miR-18a/low tumours expressed high levels of HIF1A." (PMID 38786043, 2024). "Concerning the interaction of hypoxia and acidosis, stabilization of hypoxia factor HIF1α was demonstrated in macrophages under the effect of tumor-derived lactate and succinate in hypoxic and normoxic conditions, which results in production of VEGF and, consequently, enhanced tumor angiogenesis." (PMID 38794298, 2024).
tumor (continued). "These in vivo results were well in agreement with the in vitro experiments, providing strong evidence that the HIL@Z/P/H+Red+NIR treatment maybe alleviate tumor hypoxia to inhibit lung metastasis by downregulating the levels of HIF-1α and MMP-9." (PMID 38280861, 2024). "In summary, our results demonstrated that NREP could be transcriptional activated by HIF-1α, which may aggravate BC tumor growth and metastasis by promoting cellular glycolysis." (PMID 38697993, 2024). "Notably, the tumor region still displayed the maximal fluorescence signals of HIF-1α relative to major organs, indicating that EcN-cypate can still target the hypoxic tumor after HBO treatment." (PMID 38886343, 2024). "Additionally, CAF-mediated activation of HIF-1α can lead to the upregulation of the immune-inhibitory PD-L1 on both immune cells and tumor cells." (PMID 39696386, 2024). "We hypothesized that radiation could improve hypoxia in the microenvironment of NSCLC brain metastases, downregulate HIF-1α expression, and cause a decrease in MIF release from tumor cells." (PMID 38685050, 2024). "IHC analysis, in mice receiving daily HIF-1α siRNA injections has confirmed the macroscopic image of reduction of tumor volume through the decreased levels of HIF-1α transcriptional targets, like VEGF, GLUT–1, c-MET, and CA-IX and markers for cell growth like MIB-1 and MVD." (PMID 39055895, 2024). "Moreover, the amount of adenosine produced by tumor cells regulated by HIF-1α increased in the hypoxic microenvironment." (PMID 39192979, 2024). "The changes in tumor tissue hypoxia before and after treatment were observed by measuring oxygen partial pressure directly with in tumor tissue and immunohistochemical staining for hypoxia-inducible factor-1α (HIF-1α)." (PMID 39872052, 2024). "Intriguingly, we found that propofol alone could downregulate the expression of HIF-1α in tumor tissue of the CRC-PDX mouse model, which was enhanced after combination with 5-Fu, although the specific mechanism is unclear, warranting further study." (PMID 39525113, 2024). "One possible mechanism behind the IL-8 alterations could be the reduction of lactate production, which activates in HIF1α and NF-κβ in tumor endothelial cells." (PMID 39060287, 2024). "Hence, KPF NPs with the synergistic effect of ROS generation and HIF-1α inhibition exhibit superior in vitro and in vivo anti-tumor efficacy by the PDT method." (PMID 39339168, 2024). "Firstly, through analyzing RNA-seq data in the TCGA and GTEx datasets, notable increases in the expression of HIF-1α and PD-L1 were observed in tumor samples compared to normal samples, and the expression of HIF-1α was positively correlated with PD-L1 in tumor samples." (PMID 38612546, 2024). "HIF-1α shRNA could decrease the formation of blood vessels, slow tumor growth, reduce tumor size, and promote tumor cell apoptosis." (PMID 39204162, 2024). "While HIF-1α is primarily known for its role in the cellular response to hypoxia, oxidative stress can also stabilize HIF-1α, resulting in the transcription of genes involved in angiogenesis, glucose metabolism, and cell survival, and supporting tumor growth, angiogenesis, and metastasis." (PMID 38392321, 2024). "Moreover, inhibitors like PX-478, EZN-2968 and other small molecules targeting HIF1α effectively reduce HIF1α protein levels, contributing to tumor regression and, in some cases, leading to prolonged disease stabilization." (PMID 39697237, 2024).
tumor (continued). "Other than promoting EMT hybrid states, HIF1α regulates tumour metabolism, and these processes might be tightly interwoven." (PMID 38238426, 2024). "Then ENTPD3‐AS1 could interact with miR‐155‐5p and upregulated the expression of HIF‐1α, inhibiting cell proliferation and tumor suppression In RCC." (PMID 39431755, 2024). "Understanding how METTL3 regulates the expression of pro-angiogenic factors, such as VEGF, HIF-1α, and angiopoietins, within the tumor microenvironment could provide new strategies for anti-angiogenic cancer therapies." (PMID 39834386, 2024). "Hypoxia-induced necrotic fragments of cancer cells, like HCC cells, and HIF-1α secreted by hypoxic tumor cells recruit TLR4 to the macrophage cell membrane, activating the toll-like receptor (TLR) 4/TIR-domain-containing adaptor-inducing interferon-β (TRIF)/NF-κB pathway." (PMID 39430253, 2024). "Our current information suggests that an mTOR-dependent enhancement of ATP production and HIF-1α levels may contribute to this LMP2A-dependent enhancement in MYC-driven tumor development and potentially the need to bypass additional oncogenic mutations." (PMID 38612754, 2024). "In addition, the antiangiogenic property of PHA in HSC-3 cells was shown, as evidenced by the drug’s suppressive effect on the expression of hypoxia-inducible factor-1α (HIF-1α), a critical tumor angiogenic transcription factor." (PMID 38474118, 2024). "Furthermore, the compound TCPP-TK-PEGPAMAM-FA has been shown to stimulate lipid peroxidation and ferroptosis in tumor cells by inhibiting the HIF-1α pathway and subsequent endogenous lipid droplet biosynthesis." (PMID 38853203, 2024). "Thus, our data implied that HIF1α regulates the E/M phenotype via upregulation of mesenchymal genes; however the connection between HIF1α and p63 in regulating the E/M tumour state remained unclear." (PMID 38238426, 2024). "Tumor cells in hypoxic conditions control cancer metabolism and angiogenesis by expressing HIF-1α." (PMID 38792080, 2024). "And HIF-1α playing a major role in the tumor hypoxic microenvironment." (PMID 38678297, 2024). "TME hypoxia induces tumor cells to secrete the hypoxia-responsive transcription factor HIF-1α." (PMID 39430253, 2024). "The study also features a novel association of low miR-18a levels and subsequent enrichment of hybrid E/M cells, increased migration and stemness in a subgroup of ER-negative tumours that may be attributed to HIF-1α mediated signalling." (PMID 38786043, 2024). "Our findings suggest that targeting the AHR could hold therapeutic potential in ccRCC; the activation of this receptor, despite the constitutive HIF1A triggering, is shown to potentiate the tumour suppressor behaviour of both the AR and RB1." (PMID 39336758, 2024). "Furthermore, the inhibition of HIF-1α expression was believed to ameliorate the hypoxic conditions within the tumor microenvironment." (PMID 38794281, 2024). "Additionally, studies show that tipifarnib suppresses tumour aggressiveness in several malignancies and low-dose tipifarnib had antitumour effects only on HIF-1α-positive cells through the mTOR singling pathway, both in vitro and in vivo in GC model." (PMID 38817874, 2024). "Notably, hypoxic microenvironment can regulate hypoxia‐responsive genes via HIF‐1α, a key factor in tumor progression." (PMID 38626369, 2024). "In tumor cells, HIF1a might act not only as a molecular sensor for oxygen levels but also to monitor protein-folding capacities, ensuring cancer cells adapt to hypoxic conditions and avoid the detrimental effects of low oxygen." (PMID 38370407, 2024). "Studies have shown that cyclic hypoxia accelerates tumor growth through HIF-1α mediated adaptation." (PMID 38791951, 2024).
tumor (continued). "By targeting HIF-1α and other factors that either promote tumour hypoxia or contribute to the hypoxia cycle, the tumour itself may be halted in a state of oxygenation, thereby increasing the number of ROS during radiation and subsequent DNA damage." (PMID 38399237, 2024). "Consequently, tumor cells try to adapt to this harsh environment, mostly via the HIF-1α/VEGF pathway." (PMID 39055895, 2024). "In addition, we demonstrate the current knowledge regarding the association between HIF-1α/VEGF expression in GBM specimens and the molecular subtype of the tumor." (PMID 39055895, 2024). "Therefore, inhibition of HIF-1α emerges as a potential strategy to attenuate hypoxic cell survival and proliferation, while potentiating the anti-tumor immune response." (PMID 39698411, 2024). "The expression level of HIF-1α increases with the severity of hypoxia in tumor tissue." (PMID 38794281, 2024). "Moreover, Jianpi Jiedu Decoction significantly inhibited the cell proliferation and suppressed tumor cell migration, invasion, and angiogenesis by inhibiting the mTOR/HIF-1α/VEGF signaling pathway in CRC." (PMID 39354520, 2024). "Here, we highlight the critical role of Redox effector 1 (Ref-1) in PDAC progression and drug resistance, focusing on its redox regulation of key transcription factors (TFs) such as STAT3, HIF1α, and NF-κB, which are pivotal for tumor survival, proliferation, and immune evasion." (PMID 39635662, 2024). "Several other studies have shown that DCE-MRI can be used to characterize unfavorable microenvironments such as hypoxia, and that Ktrans is the most robust and sensitive parameter for assessing HIF-1α expression, which is significantly reduced in hypoxic tumor cells." (PMID 39323994, 2024). "Since tissue hypoxia is a normal phenomenon in tumors, future studies should investigate whether PDK1 and HIF-1α form a positive feedback loop that regulates tumor progression." (PMID 38560503, 2024). "In addition, Zeb1 exerts its biological effects by inducing glycolytic activity via the PI3K/Akt/HIF-1α signaling axis in response to hypoxia, which contributes to the cultivation of an immunosuppressive tumor microenvironment." (PMID 39596288, 2024). "Notably, CD73 expression in tumor cells is correlated to HIF1a expression and enriched in the perinecrotic niche." (PMID 38774283, 2024). "Therefore, the elevated expression of HIF-1α promotes the expression of angiogenic genes, an altered glucose metabolism, and cell proliferation, thus promoting tumor growth and progression." (PMID 38542288, 2024). "Moreover, compelling evidence suggests that hypoxia strongly influences the induction of hif‐1a‐dependent PD‐L1 expression in tumour cells, macrophages and dendritic cells, which serves as a crucial mechanism for obstructing antitumor immunity in cancer cells." (PMID 38809929, 2024). "Besides, HIF1α and MYC are associated with increased oxidant stress and play important roles in the transition of EMT-like tumor cells to MET-like state, which is necessary for metastatic colonization." (PMID 38218942, 2024). "However, the current understanding of HIF-1α in the tumor microenvironment and its corresponding small-molecule inhibitors is still in the developmental phase, yet to progress to the clinical trial stage." (PMID 38327979, 2024). "To date, SAA has been associated with a higher tumor stage, the presence of lymphovascular invasion and lymph node metastasis, increased hypoxia-inducible factor 1 alpha (HIF1α) expression, and the production of many pro-inflammatory cytokines." (PMID 39336082, 2024). "In addition, protein levels in tumor cell lysates and tumor tissues investigated by immunoblotting and IHC staining respectively, revealed an increase in HIF-1α level in tumors derived from PDLIM2 knockdown cells, and which was blocked by PX-478." (PMID 38880883, 2024). "However, we observed that the expression of HIF1α in tumor tissues was significantly lower than that in adjacent tissues in TCGA." (PMID 38263248, 2024).
tumor (continued). "Based on our data, HIF-1α may be involved in GBM tumor angiogenesis through a regulatory mechanism of miRNAs, such as miR-210-3p and miR-224-3p." (PMID 39055895, 2024). "Intratumoral stromal and vessel cells were increased in non-squamous tumors, indicating more diffuse growth patterns, whereas squamous tumors had a corresponding enrichment of tumor and i-HIF1a+ cells reminiscent of solid tumor architecture with insufficient tumor oxygenation." (PMID 39238637, 2024). "The authors conclude that tumor environmental factors such as hypoxia and nutrient deprivation activate HIF1A signaling for the maturation of AEP, which, in turn, cleaves DDX3X to promote its sequestration in the nucleus, thus initiating a nuclear DDX3X/hnRNPA1–dependent AS program in tumor cells." (PMID 38299588, 2024). "The use of the anti-vascular drug 5,6-Dimethylxanthenone-4-acetic Acid (DMXAA) in combination with the HIF-1α inhibitor Digoxin inhibited tumor growth and stimulated immunity in a melanoma model, demonstrating a significant increase in the percentage of CD8 cytotoxic lymphocytes and NK cells." (PMID 38433193, 2024). "Furthermore, G-Rh2 inhibited the tumor’s aerobic glycolytic capacity, including glucose uptake and lactate production, through the HIF1-α/PDK4 pathway." (PMID 38671369, 2024). "Silencing of HIF1A significantly attenuated DDR1‐increased tumor growth in nude mice." (PMID 39024501, 2024). "Certain noncoding RNAs can influence tumor-related biological processes by regulating HIF-1α." (PMID 38799423, 2024). "Notably, the high expression of glycolytic key enzymes such as PFKL and GAPFH, downstream of HIF1A, was identified as the driving force behind the increased activation of glycolytic metabolic pathways within tumour cells." (PMID 37994257, 2024). "HIF-1α is a crucial regulator of metabolic reprogramming in tumor cells." (PMID 39723370, 2024). "Blocking A3 ARs with specific drugs may prevent an increase in hypoxia-induced factors like HIF-1α, which promote blood vessel formation (angiogenesis) and cancer cell spread in the tumor environment." (PMID 39124905, 2024). "In the tumor, endothelial and hepatic cells, TGFβ and HIF1α activate each other." (PMID 38361941, 2024). "This suggests that HIF-1α may serve as a therapeutic target of the tumor microenvironment not only in tumor cells but also in stromal-infiltrating cells, including EC." (PMID 38725568, 2024). "Angiogenesis plays a major role in the development of these abnormal vessels; however, neovascularization via proliferation of existing endothelial cells and via hypoxia-inducible factor 1α (HIF-1α) recruitment of bone marrow-derived vascular cells also contributes to tumor angiogenesis." (PMID 38994360, 2024). "Based on data present in the literature, we support here the existing hypothesis that HO-1’s nuclear expression is strictly linked to the regulation of gene transcription, including induction of HIF-1α, which promotes tumor progression." (PMID 38791428, 2024). "HIF-2A plays a crucial oncogenic role in ccRCC, whereas HIF-1A appears to be a tumor suppressor." (PMID 38360682, 2024). "Additionally, YAP has been shown to promote the expression of HIF-1α target genes involved in glycolysis and angiogenesis, thereby contributing to tumor growth and progression under hypoxic conditions." (PMID 39272887, 2024). "The HIF-1α inhibitor PX-478 has been studied in several murine tumor models." (PMID 39596467, 2024). "TME hypoxia induces HIF-1α secretion in tumor cells, regulating EMT by enhancing TAM functions." (PMID 39430253, 2024). "However, LW6 is known to inhibit not only MDH2 but also HIF-1α (hypoxia-inducible factor 1α); LW6 is thought to suppress the growth of some tumor cells by inducing HIF-1α degradation, at least in part." (PMID 38339168, 2024).